LMNB1 (lamin B1)
Diseases named in the same sentence as LMNB1 in open-access papers (continued):
Sharing a sentence is not in itself a finding about the gene and the disease.
gastric cancer (8 papers, 2016 to 2024). A primary or metastatic malignant neoplasm involving the stomach. "Yu Z.Y., Jiang X.Y., Zhao R.R., Luo C.J., Ren Y.X., Ma Z.J., Ye H.L.,Shi W.G., Wang C., Jiao Z.Y. Lamin B1 deficiency promotes malignancyand predicts poor prognosis in gastric cancer." (PMID 35342861, 2022). "It was observed that the expression of LMNB1 was impaired in gastric cancer tissues, and LMNB1 downregulation was accompanied with higher clinical stage, invasion depth, lymph node stage, and poor prognosis." (PMID 38824174, 2024). "For instance, immunohistochemistry showed decreased expression of LMNA and LMNB1 in 7/8 primary gastric cancers and 6/8 gastric cancers, respectively." (PMID 36589746, 2022). "In gastric cancer, lamin B1 expression is reduced intumor tissue, and low levels of lamin B1 are significantlycorrelated with clinical stage severity, depth of invasion, andpoor prognosis." (PMID 35342861, 2022). "In a cohort of 71 gastric carcinoma samples, lamin B1 expression was relatively lower when compared to its expression in the stromal cells." (PMID 35328162, 2022). "In summary, the expression profiles of lamin B1 are consistent with Dp71 in gastric cancer tissues and cancer cells." (PMID 27449096, 2016). "Lamin B1 expression profile in our work is consistent with previous lamin B1 description in gastric cancer." (PMID 27449096, 2016). "The growth alteration of SGC7901-lamin B1 cell line showed that increasing lamin B1 expression can inhibit its proliferation, which presented the evidence of a tumor suppressive role of lamin B1 in gastric cancer." (PMID 27449096, 2016). "Our further steps to characterize lamin B1 and lamin B1-Dp71 protein complex in gastric cancer tissues and cell lines proved that lamin B1 to be the putative target molecule for the newly identified tumor suppressive role of Dp71." (PMID 27449096, 2016). "Further expression characterization showed reduced lamin B1 in gastric cancer tissue and cancer cells." (PMID 27449096, 2016). "In our further exploration of lamin B1 in gastric cancer, immunohistochemistry analysis was carried out in 75 paraffin-embedded gastric cancer sections; the results were consistent with previous lamin B1 characterization in gastric cancer." (PMID 27449096, 2016). "In gastric cancer cell lines AGS, SGC7901 and BGC823, decreased lamin B1 expression was also identified compared with GES-1 cells." (PMID 27449096, 2016).
ovarian carcinoma (8 papers, 2011 to 2025). A malignant neoplasm originating from the surface ovarian epithelium. "Ovarian cancers harbor homozygous deletion in the LMNB1 gene, while the loss of lamin A/C leads to poor prognosis and enhanced metastatic potential of cells." (PMID 36589746, 2022). "Treatment with CMP and FSK—potentially involving alterations in LAT1 and lamin B1 —in combination with olaparib, led to greater reductions in survival across all ovarian cancer cells tested at the lowest concentrations of olaparib." (PMID 39625235, 2025). "mRNA for lamin B1 and emerin was found to be generally higher in ovarian cancer and immortalized (HIO) cells than primary human ovarian surface epithelial (HOSE) cells." (PMID 21439080, 2011). "Thus, the effect of CMP on nuclear lamina components (lamin B1 and lamin A/C) varied among different ovarian cancer cell lines." (PMID 39625235, 2025). "We first tested if known relevant nuclear envelope components in ovarian cancer were deregulated according to cancer nuclear morphological diversification, including LMNA, Lamin B1 and B2, Emerin, nucleoporins NUP88 and NUP1532." (PMID 30254278, 2018). "It is unique that LMNB1 and LMNB2 genes showed only deep deletions in ovarian cancers." (PMID 36589746, 2022). "In ovarian cancer, FOXM1 also induces the expression of integrins and matrix proteins: ITGB1, ITGAV, ITGA5, LMNB1, and FN1, which may facilitate adhesion of ovarian cancer cells to new organs." (PMID 34205406, 2021). "In addition, nucleolin was identified in the cytoplasmic/membrane fraction (lamin B1 negative) of all ovarian cancer cells tested, but not in the one from the non-tumorigenic MCF12A control cell line." (PMID 34207464, 2021). "In addition, levels of IGFBP7, PAI-1, lamin B1, P21, P27, P62, p-H2AX, and other factors related to cell senescence were significantly elevated, indicating that S1PR1 may be involved in regulating ovarian cancer senescence." (PMID 37828220, 2023).
colon cancer (7 papers, 2019 to 2025). "To further explore nuclear bleb composition, we used HCT116 colon cancer cells with a CRISPR-labeled endogenous GFP–lamin B1." (PMID 39501901, 2025). "It has been discovered that upregulated LMNB1 can induce MC in colon cancer cells after 5-FU treatment." (PMID 35884370, 2022). "By contrast, LMNB1 was among the top25 down-regulated proteins in quantitative stable isotope labeling using amino acids in cell culture (SILAC) proteomic analysis of human colon cancer cells induced by galectin-4." (PMID 36005596, 2022). "LMNB1 was up-regulated in a 5-FU-resistant HCT116 human colon cancer sample cell line." (PMID 36005596, 2022). "Additionally, the overexpression of LMNB1 was the biomarker indicating the occurrence of retinoblastomas and poor prognosis of colon cancers." (PMID 32149105, 2020). "Thus, upregulating LMNB1 might be helpful in colon cancer therapy." (PMID 35884370, 2022).
liver cancer (7 papers, 2010 to 2022). An epithelial or non-epithelial malignant neoplasm that arises from the liver. "Another study reported that circulating LMNB1 is a diagnostic biomarker for early stage liver cancer." (PMID 36405011, 2022). "Moreover, incorporating LMNB1, Ki67 and Barcelona Clinic Liver Cancer (BCLC) stage into a nomogram showed better predictive accuracy than the Tumor-Node-Metastasis (TNM) stage and BCLC stage." (PMID 35436411, 2022). "The prognostic performance of LMNB1 has recently been reported for liver cancer." (PMID 20300185, 2010).
glioma (6 papers, 2021 to 2025). A benign or malignant brain and spinal cord tumor that arises from glial cells (astrocytes, oligodendrocytes, ependymal cells). "About their oncogenic potential, an elevated expression of LMNB1 and related proteins of the same nuclear lamina family has been associated with tumor development, aggressiveness, and metastasis in a wide variety of cancers, as well as in glioma cells." (PMID 38607010, 2024). "In a recent study based on microarray data, it was shown that LMNB1 expression was higher in gliomas, and was also related with poor survival rates." (PMID 36945359, 2023). "Our study confirmed that LMNB1 and DLGAP5 were up-regulated in gliomas, and patients with high expression of LMNB1 or DLGAP5 had poor survival rate." (PMID 33956061, 2021). "Our data showed that down-regulation of LMNB1 inhibited the proliferation of glioma cells by arresting the cell cycle at G0/G1 phase." (PMID 33956061, 2021). "Taken together, our analyses showed that LMNB1 and DLGAP5 were highly expressed in glioma and negatively associated with patient survival, indicating that LMNB1 and DLGAP5 were important for the development and prognosis of glioma." (PMID 33956061, 2021). "The analysis results showed that glioma patients with high expression of LMNB1 and DLGAP5 exhibited worse overall survival rate." (PMID 33956061, 2021). "Among four glioma subtypes (proneural, mesenchymal, classical and neural), the proneural subtype exhibited the highest expression level of LMNB1 and DLGAP5, and the neural subtype expressed the lowest levels." (PMID 33956061, 2021). "Examined by EdU and CCK-8 assay, we discovered that the percent of EdU positive cells and cell proliferation of glioma cells decreased after down-regulation of LMNB1." (PMID 33956061, 2021). "They asserted that all three of the human genes encoding for lamin isoforms (LMNA, LMNB1, and LMNB2) are significantly upregulated in glioma tissues compared with normal brain tissues and their silencing dramatically suppresses glioma progression in both in vitro and in vivo mouse models." (PMID 35883635, 2022). "Similarly, Grade IV gliomas showed the highest LMNB1 and DLGAP5 expression level in CGGA RNAseq datasets." (PMID 33956061, 2021). "It will be interesting to determine whether LMNB1 promotes glioma progression via regulating lipid synthesis in the future." (PMID 33956061, 2021). "Moreover, inhibition of LMNB1 suppressed glioma proliferation." (PMID 36945359, 2023). "We analyzed the expression of LMNB1 and DLGAP5 in glioma patients with different histological subtype, molecular subtype, progression stage and IDH status in TCGA and CGGA databases." (PMID 33956061, 2021). "LMNB1 and DLGAP5 were two potentially novel molecular biomarkers for diagnosis and prognosis of glioma." (PMID 33956061, 2021). "First, we detected the basal protein level of LMNB1 and DLGAP5 in several glioma cell lines including LN229, U87, primary cultured GBM cell (GBM), U251, T98G." (PMID 33956061, 2021). "Together, LMNB1 and DLGAP5 were two potentially novel molecular biomarkers for diagnosis and prognosis of glioma." (PMID 33956061, 2021). "However, in our system, we did not observe the increase of the percentage of >4N polyploid cells in glioma cells by flow cytometry, indicating that silencing LMNB1 could not induce mitotic mutation." (PMID 33956061, 2021). "Consistent with the online analyses, we found that down-regulation of LMNB1 and DLGAP5 with siRNA inhibited the proliferation of glioma cells." (PMID 33956061, 2021). "After searching for TCGA and CGGA datasets, we found that the expression of LMNB1 and DLGAP5 were up-regulated in glioma." (PMID 33956061, 2021). "In addition, LMNB1 and DLGAP5 were selected for further analyses due to their high expression in gliomas and were verified by using our cohort." (PMID 33956061, 2021).
glioma (continued). "Since both of LMNB1 and DLGAP5 were up-regulated in glioma tissues, we therefore down-regulated LMNB1 and DLGAP5 with siRNAs to detect whether silence of LMNB1 or DLGAP5 inhibits the proliferation of glioma cells." (PMID 33956061, 2021). "Furthermore, we researched the roles of LMNB1 and DLGAP5 in glioma cell proliferation by silencing LMNB1 and DLGAP5." (PMID 33956061, 2021). "In conclusion, these results showed that LMNB1 and DLGAP5 may be used to predict the prognosis of glioma patients." (PMID 33956061, 2021). "Silence of LMNB1 and DLGAP5 inhibited the proliferation of glioma cells." (PMID 33956061, 2021). "Together, these data indicated that LMNB1 and DLGAP5 were up-regulated in glioma and might play specific roles in different molecular subtype." (PMID 33956061, 2021). "In addition, silence of LMNB1 arrested the cell cycle of glioma cells at G1 phase, but did not affect the percentage of >4N cells in total cells." (PMID 33956061, 2021). "Furthermore, silence of LMNB1 and DLGAP5 inhibited the proliferation of glioma cells." (PMID 33956061, 2021). "Compared with non-tumor tissues, LMNB1 and DLGAP5 were highly expressed in glioma tissues, which was reflected in the research of Sun and Murat." (PMID 33956061, 2021). "Moreover, both senescent glioma cells (identified with GFAP, γ-H2AX, and P21 positive, and Lamin B1 negative expression) and TAMs (identified with IBA1, γ-H2AX, and P21 positive, and Lamin B1 negative expression) were reduced by GDC-0879." (PMID 40781221, 2025).
autosomal dominant adult-onset demyelinating leukodystrophy (5 papers, 2015 to 2025). "An extra copy of the LMNB1 gene at the 5q23 locus has been previously associated with autosomal dominant adult-onset demyelinating leukodystrophy (ADLD) (OMIM #169500)." (PMID 27663310, 2016).
cerebellar ataxia (5 papers, 2019 to 2025). A neurological syndrome characterized by clumsy and uncoordinated movement of the limbs, trunk, and cranial muscles. "As the only disease associated with increased lamina B1 encoded by LMNB1, ADLDs have different clinical presentations, ranging from autonomic to pyramidal tract and cerebellar ataxia." (PMID 31695592, 2019). "We also observed that the level of LMNB1, which is involved in cerebellar ataxia and adult autosomal dominant leukodystrophy (r2 = −0.634, p < 0.0001), and the level of Pi4KA (r2 = −0.634, p = 0.066) in the hippocampus were correlated with the DI." (PMID 37063368, 2023). "Non-classical clinical cases of LMNB1 upstream deletions reported in other countries have demonstrated late onset, lacking autonomic dysfunction and cerebellar ataxia." (PMID 40046440, 2025).
endometriosis (5 papers, 2020 to 2025). The growth of functional endometrial tissue in anatomic sites outside the uterine body. "In our previous study, we demonstrated a decrease in lamin b1 expression in endometriosis lesions compared to that in the eutopic endometrium; however, we did not consider the different phases of the menstrual cycle." (PMID 35269619, 2022). "In this study, in an enlarged subset of patients, we found a difference in lamin b1 expression during the proliferative phase, where lamin b1 concentration was lower in endometriosis lesions than in the eutopic endometrium." (PMID 35269619, 2022). "In lesions, we observed higher expression of p16Ink4a and IL-1β and lower expression of lamin b1 than in the eutopic endometrium, which indicates that senescent cell biomarkers are present in endometriosis lesions." (PMID 35269619, 2022). "In our previous study, higher p16 and depleted lamin b1 concentrations was observed in deep infiltrating endometriosis compared to that in the eutopic endometrium of patients with endometriosis to assess senescence." (PMID 36241900, 2022). "Interestingly, we observed a decrease in lamin b1 expression in endometriosis lesions compared to that in the eutopic endometrium." (PMID 35269619, 2022). "The present study demonstrated that in the same patient, the retrocervical deep-endometriosis lesion has pro-senescence characteristics, as shown by the presence of higher IL-1β and p16Ink4a expression and lower lamin b1 expression, compared to the eutopic endometrium." (PMID 35269619, 2022). "Endometriosis lesions have lower levels of lamin b1 than the endometrium." (PMID 35269619, 2022). "Q RT-PCR was used to detect the expression of ACKR1, LMNB1, MFAP4, NMU, and SEMA3C mRNA in ectopic endometrial tissues of patients with endometriosis." (PMID 36277723, 2022). "ACKR1, LMNB1, MFAP4, NMU, and SEMA3C were upregulated in ectopic endometrial tissues of patients with endometriosis compared with normal endometrium (P < 0.001), which was consistent with the results of bioinformatics analysis." (PMID 36277723, 2022). "In our study, high-quality images showed lamin b1 and p16 labeling patterns on the three distinct endometriotic lesions, eutopic endometrium, and non-endometriosis endometrium along with their glandular-epithelial and non-glandular-epithelial compartments." (PMID 36241900, 2022). "Hence, in this study, we explored this hypothesis by evaluating a group of key senescence markers, namely p16Ink4, IL-1β, lamin b1, and the SASP, in tissues of women with deep endometriosis." (PMID 35269619, 2022).
Huntington disease (5 papers, 2021 to 2025). Huntington disease (HD) is a rare neurodegenerative disorder of the central nervous system characterized by unwanted choreatic movements, behavioral and psychiatric disturbances and dementia. "Here, we provide new evidence showing that increased lamin B1 levels contribute to the pathophysiology of Huntington’s disease (HD), a CAG repeat‐associated neurodegenerative disorder." (PMID 33369245, 2021). "Consistent with our finding, increased lamin B1 levels and altered nuclear morphology have been described in the brain of the R6/1 mouse model of Huntington’s Disease." (PMID 40076840, 2025). "For instance, a brain region-specific increase in the levels of lamin B1 is found in Huntington’s disease and an extra copy of LMNB1 gene is responsible for adult-onset autosomal dominant leukodystropy." (PMID 35681456, 2022). "The study shows that increased lamin B1 levels contribute to altered nuclear function of specific neurons in Huntington's disease (HD) brain." (PMID 33369245, 2021). "Indeed, LMNB1 alterations have been related also to other neurological diseases such as Parkinson’s, Alzheimer’s, and Huntington’s diseases." (PMID 34685544, 2021).
microcephaly (5 papers, 2014 to 2022). A congenital or acquired developmental disorder in which the circumference of the head is smaller than normal for the person's age and sex. "The additional five cases ascertained from 100kGP on the basis of de novo or recurrent variants in LMNB1/2 also had microcephaly, confirming the phenotype–genotype link." (PMID 33033404, 2021). "Despite their relatively similar size, very few mutations were found in B-type lamins compared to lamins A and C. There were 13 mutations associated with LMNB1, all causing neural tube defects (NTDs) including microcephaly (n = 5), spina bifida (n = 7) and anencephaly (n = 1)." (PMID 36552829, 2022). "Taken together, this provided strong genetic evidence for heterozygous variants in LMNB1 and LNMB2 as a cause of microcephaly." (PMID 33033404, 2021). "Here we identify recurrent and de novo heterozygous variants in LMNB1 and LMNB2 in eight microcephaly patients from the DDD cohort." (PMID 33033404, 2021). "Here we report the identification of recurrent heterozygous variants in LMNB1 and LMNB2, implicating the nuclear lamina in the etiology of microcephaly." (PMID 33033404, 2021). "Besides, de novo variants were recently identified in the LMNB1 gene leading to disorganization of the Lamin B1 NL and to nuclei shape alteration in patients with microcephaly." (PMID 33918867, 2021). "Following identification of variants in LMNB1, we assessed whether variants in its close homolog LMNB2 were also associated with microcephaly." (PMID 33033404, 2021). "Knockout of Lmnb1/2 or Lmnb1 alone also results in microcephaly." (PMID 24495672, 2014). "The pathogenic variants reported here are most likely dominant negative rather than haploinsufficient given that microcephaly is not present in the Lmnb1+/− mouse." (PMID 33033404, 2021).
acute myeloid leukemia (4 papers, 2018 to 2025). Acute myeloid leukemia (AML) is a group of neoplasms arising from precursor cells committed to the myeloid cell-line differentiation. "Investigations into myelodysplastic syndromes and acute myeloid leukemia (AML) have unveiled a notable association between lamin B1 and chromosomal aberrations." (PMID 39866838, 2025). "In a mouse model of acute myeloid leukemia, qPCR analysis of bone marrow cells revealed elevated expression of aging markers Cdkn2a, Cdkn1a, and SASP factors, while the expression of Lmnb1 was reduced." (PMID 39963130, 2025). "Importantly, sole morphometric parameters have a unique diagnostic capacity, e.g., the expression of lamin A/C distinguishes healthy from neoplastic T cells, whereas lamin B1 suggests the presence of acute myeloid leukemia (AML)." (PMID 37176128, 2023). "Intriguingly, we found decreased Lamin B1 in other non-lymphoid malignancies including acute myeloid leukaemia demonstrating that LADs are also deregulated in other haematological malignancies." (PMID 28804121, 2018).
Alzheimer disease (4 papers, 2020 to 2024). A progressive, neurodegenerative disease characterized by loss of function and death of nerve cells in several areas of the brain leading to loss of cognitive function such as memory and language. "Primary rat hippocampal neurons in long‐term cultures show molecular changes indicative of both senescence (senescence‐associated β‐galactosidase, p16, and loss of lamin B1) and proteostasis failure relevant to Alzheimer's disease." (PMID 31762159, 2020). "Although there are some reports indicating the increased levels of lamin-A in late stages of Alzheimer’s disease, lamin-B1 is reportedly more important for neurons." (PMID 36806186, 2023).